Y_RNA (Y RNA )
Gene: Miscellaneous RNA gene on chromosome 1 (165,662,585 to 165,662,687, reverse strand). Ensembl gene ENSG00000206990.
Homologues: Orthologues: chimpanzee Y_RNA (100% identical), macaque Y_RNA (96% identical), tropical clawed frog Y_RNA (75% identical). Paralogues in human: RNY3 (89% identical), Y_RNA (89% identical), Y_RNA (88% identical), Y_RNA (87% identical), RNY3P1 (86% identical), Y_RNA (86% identical), Y_RNA (85% identical), Y_RNA (84% identical), RNY3P16 (83% identical), Y_RNA (83% identical), RNY3P14 (83% identical), RNY3P2 (83% identical), and 96 more.